PHACTR4 (phosphatase and actin regulator 4)
Description:
Regulator of protein phosphatase 1 (PP1) required for neural tube and optic fissure closure, and enteric neural crest cell (ENCCs) migration during development. Acts as an activator of PP1 by interacting with PPP1CA and preventing phosphorylation of PPP1CA at 'Thr-320'. During neural tube closure, localizes to the ventral neural tube and activates PP1, leading to down-regulate cell proliferation within cranial neural tissue and the neural retina. Also acts as a regulator of migration of enteric neural crest cells (ENCCs) by activating PP1, leading to dephosphorylation and subsequent activation of cofilin (COF1 or COF2) and repression of the integrin signaling through the RHO/ROCK pathway (By similarity).
Synonyms: FLJ13171; PPP1R124
Tractability: Antibody: the Human Protein Atlas places it where antibodies can reach. PROTAC: ubiquitination databases record sites on it.
Gene: Protein-coding gene on chromosome 1 (28,369,563 to 28,500,364, forward strand). Ensembl gene ENSG00000204138.
Subcellular location: Cytoplasm; Cell projection, lamellipodium
Subcellular location (Human Protein Atlas): Cytosol; Plasma membrane; Intermediate filaments
Gene Ontology:
Molecular function: actin binding; protein phosphatase 1 binding; protein phosphatase activator activity
Biological process: actin cytoskeleton organization; closure of optic fissure; enteric nervous system development; negative regulation of integrin-mediated signaling pathway; neural crest cell migration; neural tube closure; positive regulation of catalytic activity; regulation of cell cycle; Rho protein signal transduction
Cellular component: lamellipodium; cytoplasm
Genetic constraint (gnomAD): Loss-of-function variants: 42 observed, 60.74 expected, observed/expected ratio (o/e) 0.69, 90% interval 0.54 to 0.89. The synonymous counts are far from expectation, so gnomAD's model fits this gene poorly and the ratio says little. Missense variants: 686 observed, 840.98 expected, observed/expected ratio (o/e) 0.82, 90% interval 0.76 to 0.87. Synonymous variants: 236 observed, 299.79 expected, observed/expected ratio (o/e) 0.79, 90% interval 0.71 to 0.88.
Homologues: Orthologues: chimpanzee PHACTR4 (99% identical), macaque PHACTR4 (92% identical), dog PHACTR4 (87% identical), rabbit PHACTR4 (86% identical), guinea pig PHACTR4 (85% identical), pig PHACTR4 (82% identical), mouse Phactr4 (80% identical), rat Phactr4 (76% identical), tropical clawed frog phactr4 (47% identical), zebrafish phactr4a (46% identical), zebrafish phactr4b (45% identical), Drosophila melanogaster CG32264 (29% identical), and 1 more. Paralogues in human: PHACTR2 (35% identical), PHACTR1 (28% identical), PHACTR3 (25% identical).
Diseases named in the same sentence as PHACTR4 in open-access papers:
PHACTR4 is named in the same sentence as 11 diseases in open-access papers, as found by Europe PMC text mining. Sharing a sentence is not in itself a finding about the gene and the disease. The quoted sentences say what the papers report.
depression (2 papers, 2025). "A recent study reported that Phactr4 upregulation in the hippocampus in a chronic stress-induced depression model correlates with NF-kB induction and IL-1β secretion." (PMID 40462895, 2025). "Phactr4 downregulation in this context decreased neuroinflammation, improved synaptic plasticity, and moderated depression-like behaviors in rats." (PMID 40462895, 2025). "Targeting phosphatase and actin regulator 4 (Phactr4) also reverses chronic stress-induced depression-like behavior in rats by regulating neuroinflammation and neuroplasticity." (PMID 40936908, 2025).
gastric cancer (2 papers, 2020 to 2025). A primary or metastatic malignant neoplasm involving the stomach. "Since two pioneering reports introduced the impact of ADAR1 on gastric cancer progression, others have reported targets including antizyme inhibitor 1 (AZIN1), the mTOR/p70S6K pathway, and phosphatase and actin regulator 4 (PHACTR4)." (PMID 39825637, 2025). "Since two pioneering reports introduced the impact of ADAR1 in gastric cancer progression, others have reported targets including Antizyme Inhibitor 1 (AZIN1), mTOR/p70S6K pathway, and Phosphatase And Actin Regulator 4 (PHACTR4)." (PMID 32867271, 2020).
breast carcinoma (1 paper, 2022). "For DNA CNV dataset, the PHACTR4 was associated with prostate, breast andcolon cancer, while RPA2 was associated with breast cancer." (PMID 36175944, 2022).
pituitary adenomas (1 paper, 2026). "With transcriptome sequencing and comprehensive bioinformatics analysis, PHACTR4 was identified as the potential target gene of miRNA-221/222 in regulating biological functions of pituitary adenoma cells." (PMID 41660554, 2026). "In conclusion, miRNA-221/222 played the role of proto-oncogene in the occurrence and development of pituitary tumors by targeting PHACTR4, which provided a new target for the diagnosis and molecular treatment of pituitary adenomas." (PMID 41660554, 2026).
West syndrome (1 paper, 2020). "The genetic dominance of West syndrome Phactr1 mutations and Phactr4 R536P/humdy mutation also is consistent with Phactr-family proteins interacting with other cellular components in addition to PP1." (PMID 32975518, 2020).
tumor (4 papers, 2020 to 2026). "It is possible that selective downregulation of Phactr4 in monocyte-derived tumor-associated macrophages (TAMs) could lead to migratory defects that prevent them from effectively penetrating the tumor microenvironment, as well as to phagocytic defects that prevent tumor cell clearance." (PMID 40462895, 2025). "In vivo experiment of subcutaneous tumor formation in nude mice verified that miRNA-221/222 promoted tumor growth by targeting PHACTR4." (PMID 41660554, 2026). "A large number of genes that function as tumour and growth suppressors, such as PHACTR4 and ARID4A, as well as genes that correspond to chemotherapy/radiotherapy response genes, such as SNAI1 and SNX1, were overexpressed." (PMID 32543350, 2020). "Interestingly, previous studies have identified PHACTR4 as a tumor suppressor in several cancers, with functions in PP1 localization and Rb dephosphorylation." (PMID 35419005, 2022). "In particular, the link between Ezrin and Phactr4 may be relevant to tumor pathogenesis." (PMID 40462895, 2025).
cancer (3 papers, 2017 to 2025). A tumor composed of atypical neoplastic, often pleomorphic cells that invade other tissues. "Phactr4 deletions and ezrin activation have been noted in several cancers, including breast, colorectal, lung, ovarian, and renal tumors." (PMID 40462895, 2025). "The control genes CEP164, PHACTR4 and MLL3 displayed as expected high mutation frequencies, ranging from 30% to 80% in the MSI cancer cell lines." (PMID 27907910, 2017).
PHACTR4 also shares sentences with these, for which no sentence is quoted: atherosclerosis (1 paper); cervical cancer (1); lymphoma (1); pituitary tumor (1).